CD4 (CD4 molecule)
Diseases named in the same sentence as CD4 in open-access papers (continued):
Sharing a sentence is not in itself a finding about the gene and the disease.
tumor (continued). "Furthermore, chemokines such as CCL5 and CXCL9 dictate CD4+ T-cell infiltration patterns within tumors, ultimately influencing the strength and nature of the anti-tumor immune response." (PMID 40860882, 2025). "The increase of MHCII expression was likely a result of the increased interferon responses in tumor cells, which was partially attributed to the increased IFNγ produced by M002-activated CD4+ T cells, according to our in vitro culture and in vivo adoptive transfer assays." (PMID 39885128, 2025). "Notably, DBI was associated with an immune landscape potentially indicative of enhanced anti-tumor responses, characterized by inverse correlations with Tregs and MDSCs, alongside positive associations with activated CD8+ and CD4+ T cells." (PMID 40426943, 2025). "Furthermore, while CD8+ T cells play a central role in direct tumor cell killing, CD4+ T cells are critical for orchestrating the overall immune response through cytokine secretion and support of other immune effectors." (PMID 40297580, 2025). "However, recent studies have demonstrated that certain cancer cells express MHC class II molecules in the tumor microenvironment, enabling them to be a target of CD4 CTLs." (PMID 40070836, 2025). "Initially, we enumerated the aggregate number of surmised ligand–receptor (LR) interactions for each T-cell category in all sample pairs, uncovering numerous predicted interaction patterns entailing CD8+ T cells, Treg cells, NK cells, and CD4+ T cells in tumor tissues." (PMID 40723292, 2025). "Additionally, PD-1 expression in tumor-infiltrating CAR+CD4+ or CAR+CD8+ T cells in the T4M828zT2 group was lower than that in the M28zT2 group." (PMID 40107245, 2025). "Thus, attenuating Treg cells and effectively activating or restoring the effector CD4 + T cell response are important factors for successful tumor clearance." (PMID 39901294, 2025). "The proportion of major cells that participate in cancer cell killing and tumor elimination, including CD4+ T cells, CD8+ T cells, mature B cells, monocytes and dendritic cells, were lower in the MO-MLPS high risk LUAD patients than those with the MO-MLPS low risk." (PMID 40761262, 2025). "Oxysterols in the tumor microenvironment induce cholesterol depletion in T cells via modulation of SREBP2/LXR, with CD8+ T cells being more susceptible to cholesterol deficiency than CD4+ T cells." (PMID 40145543, 2025). "Additionally, azvudine regulated the interactions from other tumor immune cells to CD4+ T and CD8+ T cells through ligand‒receptor pairs such as COL1A2‒(ITGA1 + ITGB1), CCL4‒CCR5, CCL6‒CCR2, and CXCL16‒CXCR6." (PMID 39819859, 2025). "Additionally, by scrutinizing cells that share TCRαβ in paired blood and tumors, and tracking their phenotype, we identified cytotoxic CD4+ T cells with matching TCRs in blood and tumor." (PMID 40299576, 2025). "Exploration of the tumour microenvironment via the “ssGSEA” algorithm revealed differential enrichment of immune cells, with Cluster A showing a greater abundance of immune cells than Cluster B, except for natural killer cells, monocytes and CD4+ T cells." (PMID 40181975, 2025). "Moreover, low-risk patients displayed a higher proportion of CXCL13 + CD4+ and CXCL13 + CD8 + T cells, indicating a more active tumor immune microenvironment and enhanced responsiveness to immunotherapy." (PMID 40670378, 2025). "It is critical to assess for cytologic atypia when reviewing CD3-stained slides, and institutions should ensure quality control in immunostaining techniques, tumour cells generally express either CD4 or CD8, although they may sometimes lack both markers." (PMID 41561549, 2025). "First, further experimental validation through clinical and functional assays is necessary for the distinct immunophenotypic profiles and functional characteristics identified in this study for the tumor-infiltrating myeloid cells, CD4+ and CD8+ T lymphocyte subsets, and B lymphocyte populations." (PMID 40145099, 2025).
tumor (continued). "CD4+ T cells engineered to express MHC-I-restricted TCRs can directly target tumour cells instead of relying on MHC-II expression, typically only constitutively expressed on antigen-presenting cells (APCs) or induced on endothelial cells following inflammatory stress." (PMID 40801654, 2025). "Additionally, pan-cancer analysis shows that s1-CAF enrichment creates an immune-excluded microenvironment, leading to reduced T cell infiltration in the tumor bed and increased proportions of CD4+ Tregs and CD8+ exhausted T cells (Tex)." (PMID 40890855, 2025). "Further, CD27+ CD4+ T cells and LAG-3+ CD8+ T cells displayed significant positive correlations between PB and tumor tissues, whereas a positive association of 4-1BB+ CD4+ or OX40+ CD4+ T cells derived from ascites and tumor samples was detected." (PMID 41221283, 2025). "Moreover, CTLs primed in the presence of CD4+ T cell help possess enhanced, cell‐intrinsic abilities to traffic to the tumor site and consequently control the tumor." (PMID 40667699, 2025). "Because most tumors are MHC class II negative, we assume that IFNγ produced by vaccine-specific CD4+ T cells can upregulate HLA-DR expression in tumor cells, making them susceptible to lysis." (PMID 40543509, 2025). "The ability of mTAK-500 to drive antitumor efficacy via an innate-to-adaptive immune cell engagement was further supported by the selective elimination of MDSCs, tumor-associated macrophages (TAM), DCs, and CD4+ or CD8+ T cells prior to treatment with mTAK-500." (PMID 39918395, 2025). "In addition to inhibiting CD8+ T cell function or affecting tumor antigen-specific CD4+ T cell differentiation, Treg also impact the overall function of the cancer-immunity cycle." (PMID 40385461, 2025). "Thus, the proportion of PD-1+ cells, especially in transformed CD4+ T-cells expressing Meq, increased in the spleen and tumor tissues of chickens with MD." (PMID 40430752, 2025). "Numerous studies underscore the pivotal role of CD4 + T cells in antitumor immunity, demonstrating their capacity to directly eliminate tumor cells and coordinate tumor destruction through cytokine production within the tumor microenvironment (TME)." (PMID 40358736, 2025). "This study demonstrates that CD5 expression in CTCL is largely dependent on lesion type, with malignant CD4 T cells from patch/plaque MF lesions showing elevated CD5 transcript levels compared to malignant CD4 T cells from MF tumor lesions and healthy control CD4 T cells." (PMID 41226451, 2025). "Furthermore, it induced an anti-tumor immune response including increased numbers of CD4+ and CD8+ T lymphocytes which in turn improved survival." (PMID 41446741, 2025). "A lower CD4+/CD8+ ratio was linked to better response rate of the patients, while multiple studies suggest an 1:1 ratio as the most beneficial in terms of anti-tumor effect." (PMID 41346587, 2025). "CD4+ T lymphocytes are important for recruiting and regulating adaptive immune responses, with their subtype distribution varying throughout carcinogenesis stages, indicating their role in tumor progression." (PMID 39858472, 2025). "In lymph nodes, the FL tumor microenvironment principally consists of CD4+ T regulatory cells (Tregs), CD4+ T follicular helper (Tfh) cells, CD8+ T cells, dendritic cells (DCs), macrophages, fibroblastic reticular cells (FRCs), and a smaller proportion of neutrophils and natural killer (NK) cells." (PMID 39828715, 2025). "Additionally, CD4-positive T cells enhance anti-tumor immune responses indirectly by activating other immune cells, such as CD8-positive T cells." (PMID 41001043, 2025). "Furthermore, anlotinib has been shown to inhibit tumor growth by inducing tumor vascular normalization and remodeling the immune-tumor microenvironment through the modulation of CD4+ T cells." (PMID 40177243, 2025).
tumor (continued). "Similarly, preclinical data support that MCT1 inhibitors selectively inhibit tumor growth but spare the functional status of CD4+/CD8+ T cells and potentiate the synergistic effects of targeting tumor cells and regulating the TIME." (PMID 41346571, 2025). "Recruited GATA-3+ CD4+ Th2 cells contribute to tumor progression." (PMID 40453074, 2025). "Additionally, CD4+ T cells can further promote the antitumor activity of CD8+ T cells by modulating immunosuppressive cells in the tumor microenvironment, such as Tregs and MDSCs (Myeloid-Derived Suppressor Cells)." (PMID 40936903, 2025). "Furthermore, in the AAV-miR-96, there was a notable rise in the proportion of CD8+ T cells and CD4+ T cells within CD3+ lymphocytes in the tumor, spleen, and peripheral blood." (PMID 41350707, 2025). "Moreover, patients with higher microbiome diversity showed increased CD4+ lymphocyte tumor infiltration and activation of CD4+ T-cell subsets expressing ki67+ and CD69+ during radiotherapy." (PMID 40191729, 2025). "These computational findings collectively indicate that BCL10 may orchestrate an immunosuppressive TIME by dual mechanisms: suppressing anti-tumor immunity via cytotoxic cell inhibition and amplifying immune tolerance through Treg/CD4+ Th2 cells potentiation." (PMID 40539049, 2025). "Moreover, the antitumor effect of IFNα–IMQ combination therapy was abolished in treated c-JunΔ/ΔCD11c-Cre mice, with a reduction in tumor-infiltrating CD4+ T cells." (PMID 39849091, 2025). "In addition to imaging, the efficacy of immunotherapy pembrolizumab in the presented case was also demonstrated by the post-treatment increase in the infiltration of CD8 + T cells within the tumour and the decreased CD4 +/CD8 + ratio." (PMID 40341577, 2025). "These cells have been hypothesised to act as a competitive decoy for the tumour specific CD4+ T cells in an environment where tumour neoantigens are limited." (PMID 40379112, 2025). "Increased CD4 + T cells; Enhanced functional activity of tumor-specific BsAbs." (PMID 40698086, 2025). "Of note, consistent with the preceding findings, both flow cytometry and immunohistochemistry demonstrated a pronounced increase in the proportion of tumor-infiltrating Th17 cells within the CD4+ T cell population in chimera-treated tumors relative to PBS controls." (PMID 41402667, 2025). "These molecular signals stimulate the production of type I interferons (IFNs) and other proinflammatory cytokines, activating dendritic cells, macrophages, and other antigen-presenting cells (APCs), which in turn prime tumor- and virus-specific CD4+ and CD8+ T cells." (PMID 40805247, 2025). "have also been reported to exert an immunomodulatory role that results in an anti-tumor effect derived from an increase in the infiltration of CD4+ and CD8+ lymphocytes in subcutaneous tumors induced in vivo, thus supporting the findings obtained in the present study." (PMID 41010517, 2025). "Notably, the predominant signature of T cells in TLSs were memory CD4+ T cells, which aligns with previous findings showing elevated proportions of CD4+ memory and naïve T cells in TLSs compared with the surrounding tumor tissue." (PMID 39870490, 2025). "Therefore, the combination therapy with TTFields and anti-PD-1 activates STAT1 and IRF1 through ICD in tumor tissue, enhancing the CCL2/8-CCR2 axis and CXCL9/10-CXCR3 axis, which recruits CD8+ T and CD4+ T cells to infiltrate and kill tumor cells." (PMID 40098106, 2025). "Moreover, the observation that CANTumor mice had significantly higher CD4+/CD8+ T cell ratios compared to CANRegress and CANReject groups suggested underlying differences in immune functioning and susceptibility to tumour development and maintenance." (PMID 40172096, 2025).
tumor (continued). "CD4+ T cells contribute to the immune system’s ability to combat tumor progression through their differentiation into various subtypes, such as Th1, Th2, Th17, and regulatory T cells (Tregs), among others, each with distinct cytokine expression profiles and immune-modulatory functions." (PMID 39858472, 2025). "Moreover, in aged tumor-bearing mice, IL-21 produced by CD4+ T cells induced CXCL13 secretion, thereby promoting TLS formation." (PMID 40860134, 2025). "Additionally, PD‐1 blockade had little effect on endogenous CD8+ and CD4+ T cells in our tumor model, likely due to the low abundance of tumor‐specific endogenous T cells within the model." (PMID 40492496, 2025). "The upregulation of these molecules may facilitate the proliferation of CD4+ T cells in the transformation phase and the migration and adhesion of tumor cells and immune cells, leading to the formation of solid tumors in various organs." (PMID 40673706, 2025). "For example, CD4 + T cell-derived EVs enriched with pro-inflammatory cytokines such as IFNγ, TNFα and IL-2, are taken up by macrophages to sustain M1 anti-tumor phenotype and to stimulate cGAS-independent STING activation, subsequently inhibiting CRC progression." (PMID 40908470, 2025). "Cytotoxic CD4+ T cells are also gaining recognition as important players in anti-tumor immunity." (PMID 40361239, 2025). "Survival analysis of CT-2A tumor-bearing mice treated i.t. with rIL-12 and intravenously (i.v.)with anti-CD4, anti-CD8, or anti-NK1.1 revealed that only CD8 T cell depletion significantly reduced the rIL-12-mediated anti-GB response compared with the control (IgG)." (PMID 40842154, 2025). "It is acknowledged that CD4+ T cells could differentiate into immune-stimulating and immunosuppressive cells, the balance of which plays a pivotal role in the tumor environment." (PMID 40564200, 2025). "CRT translocates to the cell surface, serving as an “eat-me” signal that enhances recognition and uptake by antigen-presenting cells (APCs), particularly dendritic cells (DCs), facilitating efficient cross-presentation of tumor antigens to CD4+ helper T cells and CD8+ cytotoxic T lymphocytes (CTLs)." (PMID 40977706, 2025). "A comprehensive screening process identified 23 immune cell types with notable distribution changes in tumor samples compared to the normal group, such as, fibroblasts, memory B cells, CD56bright NK cells, activated CD4 T cells, NK cells, immature DCs, and others." (PMID 40041860, 2025). "Thus, we first examined the activities of Fc-null and parental 9D9 on tumor-infiltrating CD4+ T cells." (PMID 40460830, 2025). "While the role of CD8+ T cells in tumor control is well-established, emerging evidence highlights the important contribution of CD4+ helper T cells in sustaining durable antitumor responses through direct cytotoxicity, cytokine production, and support of CD8+ T-cell and B-cell function." (PMID 40801653, 2025). "Interestingly, in the CD4+ T‐cell subset, also the frequency of cells expressing the anti‐inflammatory cytokine IL‐10 was significantly higher in the three tumor layers compared with PB." (PMID 40498413, 2025). "Based on these interpretations, it is necessary to determine the dependency of ICOS on both irAE pathology and antitumor immunity, especially in terms of the infiltration of Tregs and CD4+ T cells into tumor sites and tissues with irAEs, and their ICOS expression." (PMID 40198121, 2025). "We hypothesized that the activity of cytotoxic CD4+ T cells is gated by engagement of KLRG1 by E-cadherin on tumor cells via direct interaction." (PMID 40299576, 2025). "Notably, accumulating evidence indicates that CD4+ T cells possess independent functions that contribute to the priming of anti-tumor immunity." (PMID 40857744, 2025).
tumor (continued). "We analyzed the relationship between tumor‐infiltrating immune cells (CD4, CD8, FOXP3, CD163‐positive cells) and proteins (TGFβ1 and its downstream signal, SMAD3) expression and survival after the start of combined therapy with immune checkpoint inhibitors plus chemotherapy in SCLC." (PMID 41187938, 2025). "This suggested that γδT cells may enhance tumor antigen presentation through these interactions, indirectly boosting the anti-tumor ability of CD4+ T cells." (PMID 39895781, 2025). "CD4 + T cells are critical for orchestrating immune responses, while macrophages and neutrophils, depending on their polarization, can either support anti-tumor immunity or facilitate tumor progression." (PMID 41266441, 2025). "Because Th2 polarization inhibits Th1 differentiation and IFN-γ secretion, the trogocytosis-mediated Th2 polarization of CD4 T cells inhibits Th1-mediated anti-tumor immunity, which contributes to the development of the immunosuppressive tumor microenvironment." (PMID 39741180, 2025). "Lymphocytes are crucial components of the body’s defense against tumors, with CD8 + T cells directly attacking tumor cells and CD4 + T cells secreting cytokines and antibodies to activate NK cells and CD8 + T lymphocytes, thereby exerting their anti-tumor effects." (PMID 40597731, 2025). "Tumor antagonist immune cells include effector T cells (such as cluster of differentiation 8 [CD8+] cytotoxic T cells and CD4+ effector T cells), natural killer (NK) cells, dendritic cells, M1-type macrophages and N1-type neutrophils, which contribute to suppress tumor growth." (PMID 40270603, 2025). "Indeed, depletion of CD8+ or CD4+ T cells abolished the survival extension of CT2A tumor–bearing mice induced by the treatment with cilengitide in combination with WP1066 or AR-A014418." (PMID 40131864, 2025). "Importantly, we found that Lac treatment reduced the percentage of Tregs among the tumor-infiltrating CD45+CD4+ population." (PMID 39979425, 2025). "The observed reduction in CD4+ T cells, macrophages, and Th17 cells 38 may impair anti-tumor immune surveillance, as these cells are crucial for antigen presentation, modulation of the tumor microenvironment, and inflammatory responses." (PMID 40535813, 2025). "Moreover, GSDMD-N accumulation was also found on the plasma membrane of tumor-infiltrating CD4+ T cells in tumor sections." (PMID 40759573, 2025). "Meanwhile, CD4+ follicular helper T cells (Tfhs) provide help for tumor-specific B cell activation." (PMID 41030446, 2025). "Additionally, CD4 T cells can provide essential support for humoral immunity and exert direct cytotoxic effects on tumor cells." (PMID 40575173, 2025). "Given the important role of CD4+ T cells in tumor immune surveillance, cDC2s may also contribute to antitumor immunity." (PMID 41200280, 2025). "The balance and composition of these CD4+ T cell subsets critically influence tumor immunogenicity." (PMID 40176817, 2025). "Interestingly, a recent study has discovered that CD4 Th1 cells, along with myeloid cells, can exert a cytolytic effect on tumor cells via IFN-γ and TNF-α." (PMID 40564173, 2025). "Th2-polarized CD4+ T cells produce cytokines (e.g. IL-4, IL-13) that can dampen Th1 responses and impair the function of cytotoxic T lymphocytes, thereby weakening the immune system’s ability to attack tumor cells." (PMID 41403933, 2025). "Gemcitabine has also been shown to play a variety of immune modulatory effects in cancer, such as depleting Tregs, improving CD8+/CD4+ T-cell infiltration, depleting immune suppressive myeloid populations and improving tumor cell sensitization to immune recognition." (PMID 40768602, 2025). "Among the proteomic markers, elevated levels of serum ceruloplasmin, MYO1B, salivary CPLANE1, serum albumin, HSP 27, gamma actin, SCC 1, and A4, serum SNCG and SCCAg and immune cell markers such as, IL‐6, TNF‐α, and CD4 + T cell were suitable proteomic tumor markers in detecting OSCC." (PMID 40256126, 2025).